IL18RAP (interleukin 18 receptor accessory protein)
Diseases named in the same sentence as IL18RAP in open-access papers (continued):
Sharing a sentence is not in itself a finding about the gene and the disease.
inflammation (1 paper, 2015). Aberrant reaction of the microcirculation characterized by movement of fluid and leukocytes from the blood into extravascular tissues. "IL18rap, MMP10 and Irs1 have been recently shown to play a role in the pathogenesis of CNS inflammation." (PMID 25993608, 2015).
neurodegenerative disease (1 paper, 2022). A disorder of the central nervous system characterized by gradual and progressive loss of neural tissue and neurologic function. "Therefore, the involvement of the IL18RAP 3′UTR in other ALS-associated genetic backgrounds remains to be experimentally explored, as is the relevance to other neurodegenerative diseases." (PMID 35361972, 2022).
IL18RAP also shares sentences with these, for which no sentence is quoted: COVID-19 (6 papers); ulcerative colitis (3); allergic reactions (2); atopic dermatitis (2); breast carcinoma (2); cardiovascular disease (2); colitis (2); colon adenocarcinoma (2); periodontitis (2); abscess (1); acute myeloid leukemia (1); Allergy (1); bacterial infections (1); Behcet disease (1); bladder urothelial cancer (1); colorectal cancer (1); coronary atherosclerosis (1); diffuse large B-cell lymphoma (1); endocervical adenocarcinoma (1); esophageal adenocarcinoma (1); head and neck squamous cell carcinoma (1); HIV-1 infection (1); infection (1); infectious disease (1); kidney chromophobe (1); lung adenocarcinoma (1); lung carcinoma (1); lung squamous cell carcinoma (1); lymphoid neoplasm (1); multiple sclerosis (1).
A further 21 diseases each share a sentence with IL18RAP in 1 paper.